HPSE2 (heparanase 2 (inactive))
Diseases named in the same sentence as HPSE2 in open-access papers (continued):
Sharing a sentence is not in itself a finding about the gene and the disease.
glomerular disease (1 paper, 2023). "Here, we quantified HPSE2 expression in the renal cortex during experimental glomerular diseases to gain a better understanding of the regulation of endogenous HPSE2." (PMID 37180718, 2023). "Discussion: Taken together, our data suggest a protective effect of HPSE2 in (experimental) glomerular diseases and support the therapeutic potential of HPSE2 as HPSE1 inhibitor in glomerular diseases." (PMID 37180718, 2023). "Since we were able to show a positive effect of HPSE2 treatment on renal function in experimental models for glomerular diseases, our data strongly adds to the current body of literature on the promise of HPSE2 as a therapeutic in glomerular diseases." (PMID 37180718, 2023). "Nevertheless, these results confirm our findings in LPS-induced glomerulonephritis and suggest that the protective effect of HPSE2 might be applicable for other glomerular diseases in which HPSE1 activity has been shown to play a role." (PMID 37180718, 2023). "In conclusion, we found that HPSE2 expression was downregulated in experimental glomerular disease models for glomerulonephritis, diabetic nephropathy and adriamycin nephropathy, a model for FSGS, which is suggested to be linked to the increased HPSE1 activity in these diseases." (PMID 37180718, 2023). "Collectively, these findings indicate that reversing the observed decrease in endogenous HPSE2 expression in glomerular diseases can be an interesting therapeutic strategy, which may be mediated by HPSE1 inhibition." (PMID 37180718, 2023). "Getting a better understanding of the regulation of the natural HPSE1 inhibition by HPSE2 is valuable, since HPSE1 plays a prominent role in the manifestation of various glomerular diseases." (PMID 37180718, 2023). "We showed that besides the full-length HPSE2 protein also specific HPSE2-derived peptides can be effective in inhibition of HPSE1 activity and the treatment of glomerular diseases." (PMID 37180718, 2023). "Apparently, the effect on HPSE2 regulation in experimental glomerular diseases seems to be reversed by inhibition or lack of HPSE1 expression and activity." (PMID 37180718, 2023). "We investigated whether the observed decreased expression of HPSE2 can be attributed to increased levels of HPSE1, since HPSE1 expression and activity are increased in glomerular diseases." (PMID 37180718, 2023).
head and neck cancer (1 paper, 2025). A primary or metastatic malignant neoplasm affecting the head and neck. "Indeed, in head and neck cancer, overexpression of HPSE2 leads to increased SOX2 levels, reduced tumor growth and vascular density, and higher HPSE2 levels were associated with better survival of patients." (PMID 40899692, 2025).
intervertebral disc degeneration (1 paper, 2016). "Our data confirm that the isoform HPSE2 are also possibly involved in the development of intervertebral disc degeneration, due to increased expression compared to the non-degenerative discs." (PMID 26997908, 2016).
malignant thyroid tumors (1 paper, 2015). "Also, HPSE2 was established as an accurate marker in the distinction between benign and malignant thyroid tumors with real potential application for diagnosis in clinical practice." (PMID 26488476, 2015).
nodular goiter (1 paper, 2015). Goiter characterized by discrete tissue mass(es) that may or may not produce thyroid hormones. "Both cases of PTC presented high cytoplasmatic expression of HPSE2 on follicular cells and absence in colloidal areas when present; benign lesions demonstrated no expression of HPSE2 with just one case of colloidal expression in a nodular goiter." (PMID 26488476, 2015).
Obesity (1 paper, 2022). Accumulation of substantial excess body fat. "The identified CpGs have the potential to improve our understanding of the underlying biological pathways in the connection between obesity and lung function, with 2 CpGs (cg19088553 on gene GRIK2 and cg00612625 on gene HPSE2) having the potential for causal association with lung function." (PMID 35906571, 2022).
pulmonary diseases (1 paper, 2022). "Although we were not able to assess the biological functionality of these CpGs due to the lack of expression data of their mapped genes (GRIK2 and HPSE2) in whole blood, earlier studies have linked both genes with pulmonary diseases." (PMID 35906571, 2022).
spinal muscular atrophy (1 paper, 2024). A motor neuron disease that affect the muscles, and characterized by muscle weakness and atrophy resulting from progressive degeneration and irreversible loss of the anterior horn cells in the spinal cord (i.e., lower motor neurons) and the brain stem nuclei. "Factoring weight for weight, the dose of AAV9 vector administered to the Hpse2 mutant mice in the current study is of a similar order of magnitude as those used to treat babies with spinal muscular atrophy." (PMID 38990208, 2024).
Stillbirth (1 paper, 2025). Death of the fetus in utero after at least 22 weeks of gestation. "Therefore, a loss-of-function mutation in HPSE2 is a probable candidate cause of stillbirths in the Icelandic Cattle population, but LD suggests that there might be two independent factors affecting survival in the region." (PMID 40451979, 2025).
thyroid nodule (1 paper, 2015). A small circumscribed mass in the THYROID GLAND that can be of neoplastic growth or non-neoplastic abnormality. "The present study showed that HPSE2, used as a single marker for DTC, achieved accuracy of 86.1%, as high as observed in the other three markers, without false-negative cases, which means this molecule has great potential as a marker in the differential diagnosis of thyroid nodule." (PMID 26488476, 2015).
type 1 diabetes (1 paper, 2022). "The HPSE2 was previously reported to be associated with type 1 diabetes and the LINC00523 was associated with type 2 diabetes." (PMID 35769078, 2022).
cancer (13 papers, 2013 to 2025). A tumor composed of atypical neoplastic, often pleomorphic cells that invade other tissues. "Among the 49 obtained methylation sites, 13 showed a significant correlation with HPSE2 expression (cor < − 0.3; P < 0.05) and were significantly differentially expressed between cancer and adjacent normal tissues." (PMID 33663522, 2021). "Although the role of HPSE2 as an antagonist of HPSE1 is well appreciated in cancer, how the interaction of these proteins can affect endothelial cells is less clear." (PMID 31537875, 2019). "The expression of HPSE2 in all the three cancer tissues were down-regulated compared with the expression in normal tissue." (PMID 26084486, 2015). "In particular, MMP11 and HPSE2 were closely examined due to the important roles they play in cancer cell growth and migration." (PMID 26084486, 2015). "Based on our results, effective and targeted therapy for patients with different breast cancer subtypes can be designed and optimized for clinical application to more precisely identify and attack cancer cells by selectively inhibiting the expression of MMP11 or inducing the expression of HPSE2." (PMID 26084486, 2015). "MMPs, HPSE, HPSE2 are closely involved in cancer cells’ invasion and metastasis." (PMID 26084486, 2015). "Furthermore, this study emphasizes the role of HPSE2 in mammalian carcinomas and may offer a model to help unravel the fundamental role of its protein." (PMID 25339718, 2014). "The plasma obtained from patients with different types of cancer was able to elicit an upregulation of HPSE, HPSE2 and Syn-1 mRNA expression." (PMID 30922347, 2019). "Expressions of MMP11 and HPSE2, 2 genes closely involved in ECM-mediated cancer cell migration and angiogenesis, were found to be significantly different in breast cancer samples compared with normal controls." (PMID 26084486, 2015). "Although HPSE2 activity has not been fully characterized in any species, its antagonistic relationship with HPSE, itself an oncogene, makes it a highly likely protein to influence carcinoma." (PMID 25339718, 2014).
tumor (11 papers, 2019 to 2025). "Given its multifaceted role in the tumor microenvironment, HPSE2 regulated these key traits, underscoring the need for HPSE2-targeted therapies." (PMID 41244907, 2025). "As the most interconnected mRNA in the ceRNA network, the latest research showed that HPSE2 influenced tumor progression in multiple ways by facilitating interactions between tumors and host tissues." (PMID 41244907, 2025). "Together, these findings reinforce HPSE2 as a tumor suppressor and highlight its endogenous anti‐inflammatory activities." (PMID 40899692, 2025). "2015—Overexpression of HPSE2 attenuates tumor growth, whereas HPSE2 gene silencing promotes tumorigenesis." (PMID 37547889, 2023). "Consistently, compared with the control group, the xenografts with HPSE2 overexpression showed decreased tumor volumes." (PMID 33663522, 2021). "Through all these mechanisms, HPSE2 inhibits heparanase and thus lessens its tumor-promoting actions." (PMID 32175269, 2020). "When HPSE2 levels are elevated in response to hypoxia and endoplasmic reticulum stress, which often occur within tumors, additional tumor suppression arises." (PMID 32175269, 2020). "HPSE2 also promotes tumor suppression by downregulating the transcription factor Id1, further inhibiting heparanase activity and stimulating endoplasmic reticulum stress." (PMID 32175269, 2020). "This showed that the level of HPSE2 protein in tumor tissues was decreased below that in the adjacent tissues." (PMID 32175269, 2020). "The present study provides unprecedented evidence that HPSE2 expression can also be modulated by the crosstalk with tumor cells." (PMID 30922347, 2019). "Moreover, macrophages isolated from Hpse2‐/‐ mice showed a pro‐tumorigenic M2 phenotype, expressed higher levels of the cytokines Il‐6 and Il‐10, favored angiogenesis and promoted tumor growth in vivo compared with macrophages from WT mice." (PMID 40899692, 2025). "HPSE2 protein levels were also detected in 10 pairs of tumor tissues." (PMID 33663522, 2021). "Tumor volume was significantly suppressed after HPSE2 overexpression." (PMID 33663522, 2021). "Finally, we used six pairs of tumor tissue and adjacent tissues to detect the expression level of HPSE2 protein." (PMID 32175269, 2020). "In addition, HPSE2 could inhibit tumor cell migration, suggesting that HPSE2 might affect CRC metastasis." (PMID 33663522, 2021). "Heparanase-2 (HPSE2), a secreted protein that shares 40% homology to HPSE, interestingly does not exhibit glycosidase activity but can block HPSE activity and act as a tumor suppressor." (PMID 35294848, 2022).
infection (3 papers, 2014 to 2024). The state of being infected such as from the introduction of a foreign agent such as serum, vaccine, antigenic substance or organism. "When we treated our cells with OGT 2115 to inhibit HPSE1 followed by infection with HSV-2 strain 333 for 24 h, we observed a reduction in HS staining in the non-infected, HPSE2-silenced cells and negligible differences between the PcDNA control and siHPSE2 in the infected conditions." (PMID 39772142, 2024).
benign tumors (1 paper, 2015). "Interestingly, HPSE2 immunostaining showed a markedly higher expression in malignant tissue if compared with counterpart benign tumors." (PMID 26488476, 2015). "In other words, HPSE would be partially activated, as confirmed by the virtual absence of the 50 kDa HPSE isoform in normal thyroid sample and, thus, both HPSE and especially HPSE2 would remain preferentially in colloid in the benign tumors and normal thyroid tissues." (PMID 26488476, 2015).
genetic disorder (1 paper, 2023). "Previously, mutations in HPSE2, considered to result in Hpa2-null phenotype, were identified in urofacial syndrome (UFS), a rare genetic disorder characterized by renal tract syndrome and facial dysmorphology." (PMID 37491420, 2023).
neurological disease (1 paper, 2016). "We reasoned that HPSE2 deficiency causes neurological disease in UFS because most HPSE2 mutations in UFS are predicted to be functionally null." (PMID 26315301, 2016).
HPSE2 also shares sentences with these, for which no sentence is quoted: Anxiety (1 paper); congenital lower urinary tract obstruction (1); falciparum malaria (1); frontometaphyseal dysplasia (1); glucocorticoid deficiency (1); invasive breast carcinoma (1); kidney disease (1); leukemia (1); liver fibrosis (1); ovarian carcinoma (1); prediabetes (1); prune belly syndrome (1); type 2 diabetes (1).